BRINP2 (BMP/retinoic acid inducible neural specific 2)
Description:
Inhibits neuronal cell proliferation by negative regulation of the cell cycle transition.
Synonyms: DBCCR1L2; FAM5B
Tractability: Antibody: UniProt places it where antibodies can reach, with high confidence; UniProt predicts a signal peptide or a membrane-spanning region; its Gene Ontology location is reachable by antibodies, with medium confidence. PROTAC: ubiquitination databases record sites on it; its protein half-life has been measured.
Gene: Protein-coding gene on chromosome 1 (177,170,890 to 177,282,422, forward strand). Ensembl gene ENSG00000198797.
Subcellular location: Secreted
Gene Ontology:
Biological process: cellular response to retinoic acid; central nervous system neuron differentiation; negative regulation of mitotic cell cycle; negative regulation of cell cycle; nervous system development; positive regulation of neuron differentiation
Cellular component: cytoplasm; dendrite; neuronal cell body; extracellular region
Genetic constraint (gnomAD): Loss-of-function variants: 19 observed, 67.91 expected, observed/expected ratio (o/e) 0.28, 90% interval 0.19 to 0.41. The upper end of that interval is the gene's LOEUF score, 0.41, which puts it in group 1 of 6, group 1 being the genes least tolerant of losing a copy. Missense variants: 870 observed, 1,025.6 expected, observed/expected ratio (o/e) 0.85, 90% interval 0.8 to 0.9. Synonymous variants: 378 observed, 413.89 expected, observed/expected ratio (o/e) 0.91, 90% interval 0.84 to 0.99.
Homologues: Orthologues: chimpanzee BRINP2 (99% identical), macaque BRINP2 (99% identical), pig BRINP2 (97% identical), dog BRINP2 (96% identical), guinea pig BRINP2 (96% identical), rabbit BRINP2 (95% identical), rat Brinp2 (95% identical), mouse Brinp2 (95% identical), zebrafish brinp2 (62% identical), zebrafish brinp3a.1 (61% identical), zebrafish brinp3b (59% identical), tropical clawed frog brinp2 (56% identical). Paralogues in human: BRINP3 (69% identical), BRINP1 (51% identical).
Diseases named in the same sentence as BRINP2 in open-access papers:
BRINP2 is named in the same sentence as 16 diseases in open-access papers, as found by Europe PMC text mining. Sharing a sentence is not in itself a finding about the gene and the disease. The quoted sentences say what the papers report.
Anxiety (2 papers, 2016 to 2021). Intense feelings of nervousness, tension, or panic often arise in response to interpersonal stresses. "The observed changes in Brinp3−/− anxiety response, and increased Brinp2−/− locomotor activity may be relevant to the genetic variation at the 1q25.2 locus associated with patients diagnosed with ADHD, anxiety and other NDDs." (PMID 27826231, 2016). "An increase in open arm exploration was also apparent in the Brinp2/3−/− mice, consistent with the absence of Brinp3 alone, suggesting that this reduced anxiety phenotype is not modified by the absence of Brinp2." (PMID 27826231, 2016).
schizophrenia (2 papers, 2017 to 2023). A major psychotic disorder characterized by abnormalities in the perception or expression of reality. "Comparison of differential transcriptomic profiles and GWAS/WGS profiles identified 3 significant shared genes (ETS1, RGS6, BRINP2) commonly present between obesity and schizophrenia pair in both analyses." (PMID 37494308, 2023). "For five loci shared between openness and schizophrenia (BRINP2, SDCCAG8, PSORS1C1, DGKI and AK093940), the effect directions were concordant." (PMID 28533504, 2017). "Likewise, it has been discovered that BRINP2 is overexpressed and shared both in obesity and schizophrenia." (PMID 37494308, 2023).
oral squamous cell carcinoma (1 paper, 2016). "In non-NDD diagnoses, overexpression of BRINP2 (FAM5b) or BRINP3 (FAM5c) has been implicated in cancer: BRINP2 is amplified in oral squamous cell carcinoma, and BRINP3 is overexpressed in pituitary adenomas." (PMID 27826231, 2016).
vascular dementia (1 paper, 2025). A degenerative vascular disorder affecting the brain. "In a cross-ancestry analysis, variants in BRINP2 were associated with vascular dementia at a suggestive p value threshold." (PMID 40672175, 2025).
cancer (2 papers, 2016 to 2023). A tumor composed of atypical neoplastic, often pleomorphic cells that invade other tissues. "It was an interesting observation that two signaling pathways were identified in our TWM cohort: Ca++ signaling (RYR and TVPM6 mutations) and BMP (BMPER and BRINP2 mutations), which have recently suggested oncogenic functions in other cancer types." (PMID 36980598, 2023).
neurodevelopmental disorder (2 papers, 2016 to 2021). A behavioral and cognitive disorder with onset during the developmental period that involves impaired or aberrant development of intellectual, motor, or social functions. "In this study, the key aims were to determine the effect of loss of Brinp2 and/or Brinp3 on mouse anatomy and behavior, and to gain insight into the (potentially overlapping) function of these genes and their relationship with neurodevelopmental disorders." (PMID 27826231, 2016). "Genetic variation at the human BRINP2/ASTN1 and BRINP1/ASTN2 loci has been implicated in neurodevelopmental disorders." (PMID 27826231, 2016). "Two copy number variations (CNV)—one deletion and one duplication—are reported in patients with neurodevelopmental disorders (NDDs) that span the ASTN1/BRINP2 loci, suggesting that one or both of these genes is responsible for the neuropathology." (PMID 27826231, 2016).
tumor (2 papers, 2015 to 2023). "It is of note that in case 6, the Ca-signaling gene mutations were all clonal, as well as BRINP2, further suggesting a selection advantage for tumor cells with such mutation types." (PMID 36980598, 2023).
BRINP2 also shares sentences with these, for which no sentence is quoted: Alzheimer disease (1 paper); autism spectrum disorder (1); colorectal cancer (1); developmental delay (1); Infertility (1); learning disability (1); myocardial infarction (1); Obesity (1); pituitary adenomas (1).